SLC2A6 (solute carrier family 2 member 6)
Description:
Probable sugar transporter that acts as a regulator of glycolysis in macrophages (Probable). Does not transport glucose.
Synonyms: GLUT6; GLUT9; HSA011372
Tractability: Antibody: its Gene Ontology location is reachable by antibodies, with high confidence; UniProt predicts a signal peptide or a membrane-spanning region. PROTAC: its protein half-life has been measured.
Gene: Protein-coding gene on chromosome 9 (133,471,088 to 133,479,148, reverse strand). Ensembl gene ENSG00000160326.
Subcellular location: Lysosome membrane
Pathways (Reactome):
Transport of small molecules: Cellular hexose transport
Gene Ontology:
Molecular function: D-glucose transmembrane transporter activity; protein binding; dehydroascorbic acid transmembrane transporter activity; fructose transmembrane transporter activity; transmembrane transporter activity
Biological process: D-glucose transmembrane transport; regulation of glycolytic process; dehydroascorbic acid transport; fructose transmembrane transport; hexose transmembrane transport; transmembrane transport
Cellular component: lysosomal membrane; membrane; plasma membrane
Genetic constraint (gnomAD): Loss-of-function variants: 39 observed, 38.43 expected, observed/expected ratio (o/e) 1.01, 90% interval 0.79 to 1.33. The upper end of that interval is the gene's LOEUF score, 1.33, which puts it in group 5 of 6, group 1 being the genes least tolerant of losing a copy. Missense variants: 650 observed, 659.54 expected, observed/expected ratio (o/e) 0.99, 90% interval 0.92 to 1.05. Synonymous variants: 346 observed, 299.63 expected, observed/expected ratio (o/e) 1.15, 90% interval 1.06 to 1.26.
Homologues: Orthologues: chimpanzee SLC2A6 (99% identical), macaque SLC2A6 (98% identical), dog SLC2A6 (88% identical), guinea pig SLC2A6 (86% identical), rat Slc2a6 (82% identical), mouse Slc2a6 (81% identical), pig SLC2A6 (75% identical), tropical clawed frog slc2a6 (59% identical), zebrafish slc2a6 (52% identical), Drosophila melanogaster Tret1-1 (30% identical), Drosophila melanogaster Tret1-2 (29% identical), Drosophila melanogaster nebu (28% identical), and 39 more. Paralogues in human: SLC2A8 (41% identical), SLC2A10 (26% identical), SLC2A4 (25% identical), SLC2A12 (25% identical), SLC2A2 (24% identical), SLC2A1 (24% identical), SLC2A13 (24% identical), SLC2A5 (23% identical), SLC2A14 (23% identical), SLC2A9 (23% identical), SLC2A7 (23% identical), SLC2A3 (22% identical), and 1 more.
Diseases named in the same sentence as SLC2A6 in open-access papers:
SLC2A6 is named in the same sentence as 18 diseases in open-access papers, as found by Europe PMC text mining. Sharing a sentence is not in itself a finding about the gene and the disease. The quoted sentences say what the papers report.
breast carcinoma (4 papers, 2021 to 2024). "Additionally, there is a certain interaction between abnormal mRNA expression of SLC2A6, SLC2A8, SLC2A9 and prognosis in breast cancer (HR: 1.13 [1.06–1.62];p = 0.013, HR: 1.28 [1.03–1.59];p = 0.027 and HR: 0.78 [0.61–0.99];p = 0.043, respectively)." (PMID 34488531, 2021).
diabetes (3 papers, 2019 to 2022). "Our study broadens the understanding of myogenic differentiation and offers the Slc2a6-LDHB axis as a potential therapeutic target for the treatment of diabetes-associated muscle atrophy." (PMID 35850889, 2022). "Data mining the publicly available Attie Lab Diabetes Database revealed that Slc2a6 is highly overexpressed in the pancreatic islets of obese mice." (PMID 36077188, 2022). "In this study, the relatively uncharacterized solute carrier family gene Slc2a6 was found significantly up-regulated during myogenic differentiation and down-regulated during diabetes-induced muscle atrophy." (PMID 35850889, 2022). "Alterations of expression levels by diet were observed for all Slc2as/Gluts; greater than two-fold were only observed for Slc2a3/Glut3 at E12.5, for Slc2a6/Glut6 at E9.5 and E18.5, for Slc2a8/Glut8 at E9.5, E12.5 and E18.5, and for Slc2a13/Glut13 at E9.5, regardless of diabetes exposure." (PMID 31774824, 2019).
Sepsis (3 papers, 2022 to 2023). Sepsis is defined as life-threatening organ dysfunction caused by a dysregulated host response to infection. "One study identified SLC2A6, C1ORF55, DUSP5 and ROHB as key genes in sepsis (AUC>0.75) by the LASSO method, while SLC2A6 is thought to be positively associated with the level of infiltration of Th1 cells." (PMID 37456759, 2023). "The boxplot revealed 26 differentially expressed genes between the sepsis-induced ALI and control samples: Ncf2, Slc2a6, Cd44, Txnip, Slc2a1, Ubc, Hspb1, Zfp36, Arntl, Ddit4, Tnfaip3, Txnrd1, Mt1, Hmox1, Gch1, Gclc, Stat3, Egfr, Hif1a, Bach1, Socs1, Dusp1, Cdkn1a, Fth1, Steap3, and Alox12." (PMID 37081490, 2023).
breast tumors (1 paper, 2023). "Specifically, SLC2A1, SLC2A6, SLC2A10, and SLC2A13 were significantly overexpressed, whereas SLC2A3, SLC2A4, SLC2A9, SLC2A11, and SLC2A12 had downregulated expressions in breast tumors compared with those in normal breast epithelium." (PMID 37108300, 2023).
cholangiocarcinoma (1 paper, 2023). A carcinoma that arises from the intrahepatic biliary tree (intrahepatic cholangiocarcinoma) or from the junction, or adjacent to the junction, of the right and left hepatic ducts (hilar cholangiocarcinoma). "A study obtained four genes associated with ferroptosis (SLC2A1, SLC2A6, SLC7A5, ZEB1) by analyzing RNA-seq data after PDT in cholangiocarcinoma." (PMID 37894410, 2023). "PDT can up-regulate the expression of SLC2A1, SLC2A6, and SLC7A5 and inhibit the expression of ZEB1, and four ferroptosis-sensitive genes are associated with the prognosis of patients with cholangiocarcinoma." (PMID 37894410, 2023).
myeloma (1 paper, 2022). "Of the 13 members of the Slc2 family in mice, primary plasma cells and/or myeloma cells expressed SLC2A3, SLC2A6, and SLC2A8 as candidate glucose transporters in addition to SLC2A1." (PMID 36001583, 2022).
pancreatic cancer (1 paper, 2019). "Our study suggests that SLC2A6 contributes in part to the glycolytic defects that arise from pharmacological inhibition of eIF4A in pancreatic cancer cells." (PMID 31723131, 2019).
sarcopenia (1 paper, 2022). Progressive decline in muscle mass due to aging which results in decreased functional capacity of muscles. "Thus, this newly discovered Slc2a6-LDHB pathway may serve as an attractive therapeutic target against the sarcopenia caused by T2DM." (PMID 35850889, 2022). "Therefore, the Slc2a6-LDHB pathway can be a key therapeutic target for the management of T2DM-related sarcopenia." (PMID 35850889, 2022).
schizophrenia (1 paper, 2022). A major psychotic disorder characterized by abnormalities in the perception or expression of reality. "Alterations in solute carrier family genes, such as SLC2A6, SLC1A5, and SLC22A4, have been implicated in the impairment of the synaptic transmission, which seems relevant to the pathology of schizophrenia." (PMID 35012632, 2022).
tongue cancer (1 paper, 2012). A malignant neoplasm affecting the tongue. "Four novel genes of potential importance in tongue cancer development and maintenance, SH3BGL2, SLC2A6, SLC16A3 and CXCL10, were independently confirmed, validating our data." (PMID 22530001, 2012).
triple-negative breast carcinoma (1 paper, 2026). An invasive breast carcinoma which is negative for expression of estrogen receptor (ER), progesterone receptor (PR), and human epidermal growth factor receptor 2 (HER2). "In triple-negative breast cancer (TNBC), knockdown of YBX1 inhibited the expression of glycolytic genes (ENO1, SLC2A6, LDHA, PFKP, PGAM1, and GPI) and downregulated the expression of EMT-related genes and tumor migration and invasion." (PMID 41507134, 2026).
type 2 diabetes (1 paper, 2022). "Furthermore, we observe that islet SLC2A6 expression positively correlates with body mass index in human patients with type 2 diabetes." (PMID 36077188, 2022).
tumor (5 papers, 2020 to 2026). "The Slc2a family, consisting of the genes Slc2a3, Slc2a4, Slc2a5, Slc2a6 and Slc2a7, is responsible for glucose transporters, and exhibited increased transcription in WT type mice tumor compared to KO tumor." (PMID 34685767, 2021). "Additionally, lower levels of SLC2A3, SLC2A6, SLC2A9, SLC2A12, and SLC2A14 and higher levels of SLC2A1, SLC2A5, SLC2A10, and SLC2A11 had an association with advanced tumor stage." (PMID 36518662, 2022). "Results showed that GAS7 expression was associated with inhibition of tumor metastasis (p = 3.906e−07), RAI14 expression was associated with high pathological grade (p = 0.036) and advanced clinical stage (p = 0.046), and SLC2A6 expression was associated with high pathological grade (p = 9.835e−04)." (PMID 33312950, 2020). "A lower differentiation grade tumor is implied by overexpression of SLC2A1, SLC2A5, SLC2A10, SLC2A11and lower levels of SLC2A3, SLC2A6, SLC2A9, SLC2A12, and SLC2A14, emphasizing the possibility of these molecular roles for predicting the course of the tumor." (PMID 36518662, 2022). "LUAD tumor tissues showed higher mRNA expressions of SLC2A1, SLC2A5, and SLC2A12 and lower expressions of SLC2A3, SLC2A4, SLC2A6, SLC2A9, and SLC2A14." (PMID 36518662, 2022). "According to data from the UALCAN database, LUAD patients’ tumor tissues had hypomethylation of SLC2A1, SLC2A2, SLC2A5, SLC2A6, SLC2A7, SLC2A11 and hypermethylation of SLC2A3, SLC2A10, and SLC2A14 compared to normal tissues." (PMID 36518662, 2022). "In our study, we show that transcriptional levels of SLC2A1, SLC2A5 are upregulated and those of SLC2A3, SLC2A6, SLC2A9, SLC2A14 are downregulated in LUAD patients, supporting the role of SLC2A1, SLC2A5 as oncogenes and SLC2A3, SLC2A6, SLC2A9, SLC2A14 as tumor suppressor genes." (PMID 36518662, 2022). "Furthermore, SLC2A3, SLC2A6, SLC2A9, SLC2A12, and SLC2A14 levels were lower in patients with advanced tumor stages, suggesting that these genes might act as a barrier to the progression of LUAD." (PMID 36518662, 2022).
cancer (1 paper, 2019). A tumor composed of atypical neoplastic, often pleomorphic cells that invade other tissues. "As a consequence, CR-31 inhibition of SLC2A6 translation blunts the compensatory glycolytic program that is normally engaged by cancer cells subjected to ETC inhibition." (PMID 31723131, 2019). "Thus, further characterization of the contribution of SLC2A6 to glucose uptake relative to SLC2A1/3 may illuminate our understanding of cancer cell metabolism." (PMID 31723131, 2019).
SLC2A6 also shares sentences with these, for which no sentence is quoted: infection (3 papers); cardiomyopathy (1); Hernia (1); muscle atrophy (1).